EAF2 (ELL associated factor 2)
Diseases named in the same sentence as EAF2 in open-access papers (continued):
Sharing a sentence is not in itself a finding about the gene and the disease.
urothelial carcinoma (1 paper, 2020). A malignant neoplasm derived from the transitional epithelium of the urinary tract (urinary bladder, ureter, urethra, or renal pelvis). "Interestingly, some of these genes, such as ETV4, PTGES, CTBP2, FZD6, EAF2, and IKZF6, have not been implicated in urothelial carcinoma; thus, these genes are potential candidates for diagnostic, prognostic, and therapeutic biomarkers of urothelial carcinoma." (PMID 32391279, 2020).
tumor (16 papers, 2010 to 2024). "Cell co-culture experiments revealed that the chemotactic effect of tumor cells towards macrophages was intensified and that macrophages differentiated into tumor-associated macrophages (TAMs) when EAF2 was knocked out." (PMID 38969982, 2024). "In recent years, several studies have been conducted to investigate the mechanisms underlying the tumor suppressive function of EAF2." (PMID 38969982, 2024). "EAF2 (ELL-associated factor 2) is a potential tumour suppressor that binds to and stabilizes pVHL, thereby supressing HIF-1 activity." (PMID 36899934, 2023). "RNA Polymerase II Elongation Factor (ELL)-associated factor 2 (EAF2) is one of the tumor suppressors involved in prostate carcinogenesis." (PMID 27058417, 2016). "ELL associated factor 2 (EAF2) is a testosterone regulated apoptosis inducer and tumor suppressor." (PMID 23072359, 2012). "To corroborate our findings, we examined the TCGA database and found that tumor tissues exhibited lower EAF2 expression than normal tissues." (PMID 38969982, 2024). "This laid a foundation for further exploring the relationship between EAF2 and tumor immune microenvironment." (PMID 38969982, 2024). "EAF2 has been widely studied as a tumor suppressor, with researchers striving to unravel the mechanisms underlying its tumor-inhibiting properties." (PMID 38969982, 2024). "Our findings demonstrate a significant correlation between EAF2 expression and the number of TAMs infiltrating tumor tissues." (PMID 38969982, 2024). "EAF2 also reportedly binds to and stabilizes von Hippel-Lindau protein (pVHL), a tumor suppressor involved in mediating HIF1α degradation and an inhibitor of the hypoxia pathway, which suggests it is a potential metabolic regulator." (PMID 27259264, 2016). "ELL-associated factor 2 (EAF2) regulates transcription elongation and has been shown to be an androgen-responsive potential tumour suppressor in prostate by inducing apoptosis." (PMID 26935903, 2016). "In vitro and in vivo functional assays indicated that EAF2 has a tumour suppressive role in prostate cancer." (PMID 26935903, 2016). "Previous studies have demonstrated that EAF2 binds to and stabilizes pVHL, a tumor inhibitor mediating HIF1α degradation." (PMID 27259264, 2016). "A better understanding of the functional difference between EAF1 and EAF2/U19 will help us to better define the precise roles of EAF1 and EAF2/U19 in embryogenesis and tumor suppression." (PMID 20161747, 2010). "Little is known regarding the function of EAF1, but evidence clearly supports a tumor suppressive role for EAF2/U19." (PMID 20161747, 2010). "As well, we previously showed through in vitro and in vivo functional assays that EAF2/U19 serves a tumor suppressive role in prostate cancer." (PMID 20161747, 2010). "Early studies demonstrated the tumor-suppressing function of EAF2 in the prostate." (PMID 39588149, 2024). "The extension of the function of EAF2 not only leads to a better understanding of development but may also shed light on how the tumor suppressor contributes to tumor initiation and progression." (PMID 39588149, 2024). "Moreover, they claimed that the tumor-suppressive function of EAF2 is partly mediated through interaction with FOXA1." (PMID 39588149, 2024). "The primary role of EAF2 is an androgen-upregulated tumor suppressor in the prostate." (PMID 39588149, 2024). "Further results of ChIP assays revealed that SNHG22 could recruit EZH2 to the promoter regions of multiple tumor suppressor genes (E-cadherin, EAF2, ADRB2, rap1GAP and RUNX3), and modulating H3K27me3 levels to repress their transcription." (PMID 34663788, 2021). "These bioinformatic analyses further validated the tumor-suppressive role of EAF2 on NSCLC." (PMID 32878637, 2020).
tumor (continued). "In addition, transfection of prostate cancer cell lines with U19/EAF2 resulted in apoptosis and decreased tumor growth in a xenograft tumor model." (PMID 23749112, 2013). "Stromal inflammation and increased microvessel density was evident in EAF2-deficient mice on a pure C57BL/6J background at an early age and preceded the development of the histologic epithelial hyperplasia and neoplasia found in the prostates of older EAF2−/− animals." (PMID 24260246, 2013). "This may explain part of the function of EAF2 as a tumor suppressor." (PMID 39588149, 2024). "Thus, inhibiting SIAH2 may also enhance EAF2 tumor suppressive activity, in addition to inhibiting castration-resistant AR activation." (PMID 27058417, 2016). "Many previous studies have focused on the role of the EAF genes in tumor suppressor and transcriptional properties, but paid little attention to the linkage of EAF1 and EAF2 dysfunction with erythropoiesis and hypoxia tolerance." (PMID 37002435, 2023). "Notably, we observed that EAF2 was not downregulated in all tumor tissues, indicating the possibility of organ-specific function of EAF2." (PMID 38969982, 2024). "Previous studies have shown that zebrafish EAF1 and EAF2 regulate anterior and posterior pattern during zebrafish embryogenesis by suppressing canonical WNT/β-catenin signaling, which might be the mechanism for EAF1 and EAF2 in tumor suppression." (PMID 37002435, 2023). "Our observation that both EAF1 and EAF2/U19 participate with Wnt4a in a negative feedback loop in zebrafish embryogenesis may shed light on the tumor suppressive function of EAF proteins." (PMID 20161747, 2010).
cancer (10 papers, 2010 to 2024). A tumor composed of atypical neoplastic, often pleomorphic cells that invade other tissues. "Previous studies indicated that EAF (ELL-associated factor) family members, EAF1 and EAF2/U19, play a role in cancer and embryogenesis." (PMID 20161747, 2010). "Comparing the number of macrophages infiltrating cancer tissues with different levels of EAF2 expression, we found a significant increase in macrophages when EAF2 expression was low." (PMID 38969982, 2024). "In PCa, PIR was reported to enhance cancer cell proliferation by negatively regulating apoptosis induced by EAF2/U19." (PMID 30444038, 2019). "EAF2 expression in human cancer was significantly down-regulated and microvessel density was significantly increased compared to matched normal prostate tissue; furthermore EAF2 expression was negatively correlated with microvessel density." (PMID 24260246, 2013). "Genes that have been previously associated with MD and various other cancers showed differential marks that are either MD-induced (MX1, CTLA-4, EAF2 and GAL) or line-specific (IGF2BP1 and MMP2)." (PMID 23072359, 2012). "Our data suggests that EAF2 silencing can modulate the response of the statins in cancer cells such as HCT-116." (PMID 21483694, 2011).
infection (2 papers, 2011 to 2023). The state of being infected such as from the introduction of a foreign agent such as serum, vaccine, antigenic substance or organism. "Some proapoptotic molecules, including cyc1 (cyto c), caspase-2 (Casp2), Txnip and Casp7, Cebpb, Eaf2, were significantly down-/upregulated after infection with Brucella, and this could result in apoptosis of infected cells." (PMID 22216095, 2011). "Similar to WT STm infection, genes involved in the regulation of immune responses (ATF3, BATF3, ETS2, IRF9, NFκB2, MAFA, TNFAIP3), effector functions, (CCL4, CD200L, CD40, CD72, CD80, IL18) and TLR signaling, (EAF2, TLR15, TRAF3IP2, TOLLIP) were upregulated after ΔprgH STm infection in both models." (PMID 37854334, 2023).
EAF2 also shares sentences with these, for which no sentence is quoted: lung adenocarcinoma (3 papers); acute myeloid leukemia (1); allergic disease (1); anemia (1); asthma (1); autoimmune disease (1); fibrosis (1); leukemia (1); lupus (1); nephrolithiasis (1); non-small cell lung carcinoma (1); pancreatic cancer (1); prostate (1).